ZNF717 (zinc finger protein 717)
Description:
May be involved in transcriptional regulation.
Synonyms: X17; OB1; ZNF838
Tractability: Antibody: the Human Protein Atlas places it where antibodies can reach. PROTAC: ubiquitination databases record sites on it.
Gene: Protein-coding gene on chromosome 3 (75,678,660 to 75,785,591, reverse strand). Ensembl gene ENSG00000227124.
Subcellular location: Nucleus
Subcellular location (Human Protein Atlas): Nuclear bodies; Nucleoplasm; Plasma membrane
Pathways (Reactome):
Gene expression (Transcription): Generic Transcription Pathway
Gene Ontology:
Molecular function: transcription cis-regulatory region binding
Biological process: negative regulation of transcription by RNA polymerase II; negative regulation of DNA-templated transcription; regulation of DNA-templated transcription
Cellular component: nucleus; cytoplasm
Genetic constraint (gnomAD): Loss-of-function variants: 6 observed, 8.09 expected, observed/expected ratio (o/e) 0.74, 90% interval 0.41 to 1.45. That is too few expected variants to judge how well the gene tolerates losing a copy. Missense variants: 1,030 observed, 842.82 expected, observed/expected ratio (o/e) 1.22, 90% interval 1.16 to 1.29. Synonymous variants: 323 observed, 263.19 expected, observed/expected ratio (o/e) 1.23, 90% interval 1.12 to 1.35.
Homologues: Orthologues: chimpanzee ZNF717 (75% identical). Paralogues in human: ZNF33B (37% identical), ZNF658 (36% identical), ZNF182 (34% identical), ZNF605 (33% identical), ZNF334 (33% identical), ZNF33A (32% identical), ZNF41 (32% identical), ZNF585B (32% identical), ZNF484 (32% identical), ZNF12 (32% identical), ZNF235 (31% identical), ZNF28 (31% identical), and 164 more.
Diseases named in the same sentence as ZNF717 in open-access papers:
ZNF717 is named in the same sentence as 17 diseases in open-access papers, as found by Europe PMC text mining. Sharing a sentence is not in itself a finding about the gene and the disease. The quoted sentences say what the papers report.
hepatocellular carcinoma (3 papers, 2020 to 2025). A malignant tumor that arises from hepatocytes. "Variants in ZNF717 were previously observed in gastric, colorectal, and hepatocellular cancer." (PMID 32948182, 2020). "Gene ZNF717 (zinc finger protein 717) located on chr3:75786061-75790887 (hg19) encodes a transcriptional regulator, involved in cell proliferation and regulation of viral replication and transcription, which was reported to be associated with HBV-related hepatocellular carcinoma." (PMID 40110489, 2025). "ZNF717 is part of the zinc‐finger protein family, reported as a TSG by regulating the IL6‐STAT3 pathways in hepatocellular carcinoma." (PMID 39554798, 2024).
gestational diabetes mellitus (1 paper, 2020). "Recently, we reported on a 7-year-old DGS patient born to a mother with gestational diabetes mellitus in whom a 371 Kb-interstitial deletion of 3p12.3, involving the Zinc Finger Protein 717 (ZNF717), MicroRNA-1243 (MIR-1243), and MIR-4273 genes was identified." (PMID 32922396, 2020).
Intellectual disability (1 paper, 2022). "In the same study, a mutation in the ZNF717 gene has been identified among 16 other rare homozygous variants in at least two families, those of patients with Joubert syndrome—a disorder characterized by autistic behavior and intellectual disability." (PMID 35627305, 2022).
learning disorders (1 paper, 2022). "However, several studies have shown that ZNF717, HIP1, and several genes from the PRAME (Preferentially Expressed Antigen In Melanoma) family might be involved in cognitive development, learning disorders, and developmental disorders with autistic features." (PMID 35627305, 2022).
Renal insufficiency (1 paper, 2019). A reduction in the level of performance of the kidneys in areas of function comprising the concentration of urine, removal of wastes, the maintenance of electrolyte balance, homeostasis of blood pressure, and calcium metabolism. "Two miRNAs, miR-1243 and miR-4273 along with the Zinc Finger Protein 717 (ZNF717) are affected by this deletion, resulting in DiGeorge-like syndrome and renal insufficiency." (PMID 32117416, 2019).
tongue squamous cell carcinoma (1 paper, 2025). A squamous cell carcinoma that arises from the tongue. "Another study showed that ZNF717 and MUC3A are mutated in tongue squamous cell carcinoma." (PMID 40563552, 2025).
cancer (4 papers, 2021 to 2022). A tumor composed of atypical neoplastic, often pleomorphic cells that invade other tissues. "Four of the 11 affected genes were associated with different cancer types: MUC6 and ZNF717 (prostate), SPEN (breast), and STK33 (pancreas)." (PMID 33968136, 2021). "Among the 21 574 mutation positions from TCGA data, the highest recurrence was exhibited by the mutation at chr3:75 844 229, which was shared by 71 independent samples and located in about 10 kb upstream of ZNF717, although it is not recognized as a cancer-related gene." (PMID 34316701, 2021).
ZNF717 also shares sentences with these, for which no sentence is quoted: autonomic dysfunction (1 paper); Behcet syndrome (1); cervical cancer (1); colitis (1); infectious disease (1); Joubert syndrome (1); melanoma (1); pituitary adenomas (1); tumor (1); viral infection (1).